KEAP1 (kelch like ECH associated protein 1)
Diseases named in the same sentence as KEAP1 in open-access papers (continued):
Sharing a sentence is not in itself a finding about the gene and the disease.
lung carcinoma (continued). "Our work aimed first to assess the methylation pattern of KEAP1 promoter region in different histotypes of lung cancer cell lines by performing a QMSP vs pyrosequencing evaluation for the first time." (PMID 31159323, 2019). "The Keap1/Nrf-2/ARE pathway-mediated upregulation of Prdx6 mRNA expression has been reported in human lung carcinoma cells (A549) and primary rat alveolar type II cells treated with H2O2 or tert-butylhydroquinone." (PMID 31527445, 2019). "We concluded that targeting in autophagy or Keap1 must be the next essential therapeutic development for chemotherapy resistance in lung cancer." (PMID 30245856, 2018). "The interaction between NRF2 and KEAP1 can also be disrupted by somatic mutations of the NFE2L2 and KEAP1 genes, as observed in carcinomas of the lung, gallbladder, ovary, breast, stomach, liver, skin, larynx, and esophagus." (PMID 28899199, 2018). "Loss of KEAP1, a negative regulator of NFE2L2/NRF2, modulated the response to BRAF, MEK, EGFR, and ALK inhibition in BRAF-, NRAS-, KRAS-, EGFR-, and ALK-mutant lung cancer cells." (PMID 28145866, 2017). "Increased sensitivity to both glutamine deprivation as well as glutaminase inhibition suggests that Keap1 mutant lung cancers depend on glutamine-derived glutamate to support GSH synthesis." (PMID 28967864, 2017). "We have found that KEAP1 loss modulates sensitivity to inhibition of EGFR, ALK, BRAF, or MEK in lung cancer cell lines with EGFR, ALK, BRAF, KRAS, or NRAS mutations." (PMID 28145866, 2017). "Mutations in Kelch-like ECH-associated protein 1 (KEAP1) cause the aberrant activation of nuclear factor erythroid-derived 2-like 2 (NRF2), which leads to oncogenesis and drug resistance in lung cancer cells." (PMID 29050246, 2017). "Other studies have revealed that genomic alterations (mutations/deletions) or epigenetic changes (hypermethylation) in KEAP1 lead to its loss of function, along with overexpression of NRF2 and its downstream genes in lung cancer." (PMID 29050246, 2017). "Similar to mouse KP cells, human KEAP1 wild type lung cancer cells, H2009, responded to KI696 with nuclear accumulation of NRF2 and subsequent up regulation of target gene expression and total GSH levels." (PMID 28967864, 2017). "Second, CpG island hypermethylation in the KEAP1 promoter resulted in low KEAP1 expression in lung cancer cell lines and tumor samples." (PMID 26682001, 2016). "The overexpression of nuclear Nrf2 and the subsequent increase in the antioxidant defense in lung cancer cells are mainly related to genetic and epigenetic alterations of the KEAP1 and NFE2L2 genes." (PMID 27847554, 2016). "Nrf2 acts as a prosurvival factor through the expression of its cytoprotective target genes, and molecular deregulation of either Nrf2 or Keap1 is widely described in lung cancer, such as Notch family impairment." (PMID 27847554, 2016). "Thus, based on the structure-function relationship encoded Kelch_1, this indicates that the rare mutations in melanoma (e.g. KLHL4 G523R) could alter Kelch_1-mediated function as they affect equivalent positions to the canonical KEAP1 hotspot mutations reported in lung cancer." (PMID 26590264, 2016). "IHC studies in lung cancer, malignant gliomas, and breast cancer demonstrate a high frequency of Keap1 downregulation and NRF2 over-expression." (PMID 26247201, 2015). "Dominant-negative effect has been previously discovered in many genes and diseases such as Keap1 in lung cancer and TNFRSF13B in CVID (common variable immunodeficiency)." (PMID 25425654, 2014). "The current state of knowledge regarding NRF2 and KEAP1 in human lung cancer suggests that both apoptotic escape and resistance to anticancer treatments are responsible for the poor prognosis associated with elevated NRF2 levels and KEAP1 dysfunction." (PMID 23577226, 2013).
lung carcinoma (continued). "Arsenic species directly modulate several oncogenic pathways - most notably the EGFR, PI3K/AKT and the NRF2/KEAP1 pathways - and these specific pathways possess actionable targets for therapy in lung cancer." (PMID 23510327, 2013). "However, when the function of KEAP1, a protein involved in regulating cell growth, was restored in lung cancer cells, additionally, anti-tumor impact of brusatol was nullified." (PMID 40769273, 2025). "Therefore, this study allays concerns about pro-cancer survival benefit by demonstrating the efficacy of triterpenoid derivatives in a murine model of KEAP1-mutant lung cancer through reshaping the tumor immune microenvironment." (PMID 41462606, 2025). "Somatic mutations of KEAP1 and NFE2L2 genes are frequent in Non-Small-Cell Lung Cancer (NSCLCs), and show specific molecular pattern linked to different histological subtypes of lung cancer." (PMID 40563292, 2025). "When a targeted CRISPR-Cas9 genetic screen was performed to identify chromatin vulnerabilities associated with NRF2 activation in mouse lung cancer cells, genes encoding the class I histone deacetylases (HDAC) (Hdac1, Hdac2, and Hdac3) were found to be synthetically lethal with Keap1 loss." (PMID 40507333, 2025). "In this subtype of lung cancer, Zavitsanou and coworkers demonstrated that KEAP1-mutant tumors were able to suppress dendritic cell and T cell responses, creating an immunosuppressive phenotype that could drive resistance to immunotherapy." (PMID 40563292, 2025). "Our research indicates that itaconate promotes the radioresistance of KEAP1 wide-type lung cancer cells, but does not affect KEAP1 mutated cancer cells in vitro." (PMID 40482348, 2025). "Furthermore, TMB was not affected by STK11 mutations; and in fact, it was even elevated in tumors with mutant KEAP1 according to our analysis of the MSK lung cancer dataset." (PMID 41378285, 2025). "The literature on KEAP1-mutant cancers is growing, but more knowledge is needed to ascertain which treatments would provide the most benefit in this subset of lung cancer." (PMID 41462606, 2025). "Our analysis suggests that ADCs targeting MSLN may be particularly beneficial in lung cancer patients harboring dual mutations in STK11 and KEAP1 genes." (PMID 39186767, 2024). "This vulnerability makes KEAP1-mutant lung cancer cells or tumors sensitive to glucose transporter inhibition and suggests a potential therapeutic strategy to target disulfidptosis in this subset of lung cancers." (PMID 38428031, 2024). "However, CB-839 showed limited efficacy in a clinical trial that enrolled patients with KEAP1 mutant lung cancer possibly because this compound targets only one of many glutamine-dependent reactions that are essential for cancer growth." (PMID 38536921, 2024). "Indeed, FSP1 is highly expressed in KEAP1 mutant lung cancers, which have high NRF2 levels due to impaired proteasomal clearance and are resistant to GPX4 inhibition." (PMID 38908072, 2024). "Furthermore, KEAP1 knockdown lung cancer cells exhibited heightened proliferation capability and accelerated tumor development in nude-mice xenograft models." (PMID 38413563, 2024). "Based on our hypothesis that altered immune cell recruitment can drive immune suppression, we tested whether T-cell numbers or function were decreased in a model of KEAP1 KO lung cancer." (PMID 38542481, 2024). "As the top one ERs ranked by their associated interactions in lung adenocarcinoma (LUAD), KEAP1 mutation could affect treatment outcomes of ICB through modulating immune infiltration and immune‐related pathways in lung cancer." (PMID 39323009, 2024).
lung carcinoma (continued). "Thus, KEAP1 plays an important role in the lung cancer progression, however, its relationship and molecular mechanism in immunotherapy is not fully understood." (PMID 38413563, 2024). "Deletion of Keap1 have disparate effects by different ferroptosis inducers in lung cancer cells." (PMID 38189879, 2024). "Additionally, lung cancer cells defective in Keap1 are glucose dependent; when glucose levels are low, high uptake of cystine by lung cancer cells via the Nrf2/SLC7A11 axis stimulates the accumulation of intracellular disulfide bonds and depletion of NADPH." (PMID 39557840, 2024). "However, a different study revealed that combining CB839 with anti-PD-1 treatment inhibited the clonal expansion and activation of CD8 + T cells in KEAP1 and STK11 double-mutant lung cancer, resulting in a loss of therapeutic benefit." (PMID 38413563, 2024). "Subsequent research revealed that the level of FSP1 expression imparts resilience against ferroptosis in lung cancer cells with mutations in or lacking KEAP1." (PMID 38206305, 2024). "It provides a potential therapeutic target for KEAP1 mutant lung cancer." (PMID 38515565, 2024). "Similarly, activation of the NRF2- KEAP1 pathway is also observed in TKI treatments of lung cancer, breast cancer and kidney cancer, and is related to the emergence of drug resistance." (PMID 38982494, 2024). "For instance, both mutation and high amplification could be detected in EGFR, MET, and ERBB2 in lung cancer, as well as mutations in KRAS, BRAF, STK11, KEAP1 and many others." (PMID 39289779, 2024). "In addition, NRF2 and KEAP1 mutations can induce aberrant NRF2 signaling, which is commonly observed in lung cancer." (PMID 37525222, 2023). "CDKN2A/B, STK11, and KEAP1 had a high frequency of alterations in lung cancer BMs cases." (PMID 37384291, 2023). "KRAS/NRF2- and KRAS/KEAP1-mutant lung cancers are sensitive to reduced glutamine levels." (PMID 36942991, 2023). "This could lead to a new therapeutic strategy for addressing ferroptosis in KEAP1-mutant lung cancers." (PMID 37371948, 2023). "GLS1i combined with protons may be a novel treatment strategy for unresectable KEAP1 mutant lung cancer." (PMID 38075487, 2023). "STK11/KEAP1 co-mutations lead to a notable increase in the expression of ferroptosis-protective genes, including SCD and AKR1C1/2/3, as well as resistance to drug-induced ferroptosis in lung cancer cells." (PMID 37728413, 2023). "There are characteristic co-occurring mutations in KRAS mutant lung cancer such as STK11 and KEAP1." (PMID 38239281, 2023). "DHA can increase the inhibition of sorafenib on liver cancer, increase the effect of gefitinib on lung cancer by regulating the cell cycle, and increase the sensitivity of lung cancer and colorectal cancer to radiotherapy by activating of anti-oxidant Keap1/Nrf2 pathway." (PMID 36013308, 2022). "Here, Pranavi Koppula and her colleagues’ study indicates that pharmacological targeting of CoQ-FSP1 signaling to overcome KEAP1 deficiency-induced radioresistance could be a potentially effective therapeutic strategy in treating KEAP1 mutant lung cancers." (PMID 36264074, 2022). "KEAP1 mutant lung cancers are found radioresistant, which could be attributed to the ferroptosis resistance of these tumors." (PMID 36264074, 2022). "The Keap1-Nrf2 signaling pathway plays a key role in the oxidative stress response of lung cancer." (PMID 35721205, 2022). "Together, these results strongly suggest that KEAP1 deficiency upregulates FSP1 levels and that the CoQ-FSP1 signaling axis plays an important role in mediating ferroptosis resistance to class 2 FINs in KEAP1 deficient lung cancer cells." (PMID 35459868, 2022). "Moreover, Nrf2 released by Keap1 deactivation induced lung cancer metastases through suppression of Bach1 (another pivotal regulator of EMT) degradation in a Ho-1-dependent manner, so targeting Ho-1 or Nrf2 blockade can decrease lung cancer metastases." (PMID 35906617, 2022).
lung carcinoma (continued). "Furthermore, we found that BRD4 expression was positively correlated with KEAP1 expression and was predicted to be a factor binding to the KEAP1 promoter in lung cancer." (PMID 35453346, 2022). "Our data also suggest that targeting CoQ synthesis (by 4-CBA treatment) might provide another strategy to overcome radioresistance in KEAP1 mutant lung cancers." (PMID 35459868, 2022). "We made similar observations in another KEAP1 WT lung cancer cell line H23 cells: KEAP1 deletion rendered H23 cells resistant to ferroptosis induced by erastin, RSL3, but not FIN56; SLC7A11 knockdown promoted RSL3- or ML162-induced ferroptosis in H23 cells but not in KEAP1 KO counterparts." (PMID 35459868, 2022). "Interestingly, BRD4 showed a strong positive correlation with KEAP1 expression in three major lung cancer subtypes, including LUAD, LUSC, and SCLC." (PMID 35453346, 2022). "For example, gain-of-function mutations within the Keap1-binding domain of Nrf2, specifically within the DLG motif (e.g. L30F) and ETGE motif (e.g. T80R), impair its recognition by Keap1-Cul3, leading to the dysregulation and subsequent hyperactivation of Nrf2 in lung cancer." (PMID 35088844, 2022). "They demonstrated that Keap1/Nrf2 pathway promotes PD-L1 expression in the microenvironment from the perspective of metabolism and tumor immune microenvironment, thus providing a new target for lung cancer immunotherapy." (PMID 36439878, 2022). "While BAP1 has been regarded as a tumor suppressor possessing diverse molecular mechanisms, we reveal a possibility that BAP1 might serve as a redox regulator to inhibit NRF2 target genes and suppress the growth of lung cancer cells by deubiquitinating KEAP1." (PMID 35052618, 2022). "Since FSP1 operates in the same pathway with CoQ to suppress ferroptosis, we further tested whether inhibiting CoQ biosynthesis has any effect on radiosensitivity in lung cancer cells with KEAP1 inactivation." (PMID 35459868, 2022). "To test this hypothesis, we sought to identify a downstream effector of KEAP1 involved in the CoQ pathway in lung cancer." (PMID 35459868, 2022). "It is well acknowledged that Nrf2 activation plays a critical role in various human cancers, such as hepatocellular carcinomas, lung cancer, and gallbladder cancer.Under basal conditions Nrf2 is polyubiquitinated by the Keap1-Cul3-E3 ligase and degraded by the 26S-proteasome." (PMID 35534896, 2022). "Furthermore, targeting the CoQ10-FSP1 axis sensitizes Keap1 mutant lung cancer cells or tumors to radiation by inducing ferroptosis." (PMID 36105219, 2022). "Non‐small cell lung cancer (NSCLC), which accounts for ~ 80–85% of all lung cancer cases, exhibits mutations, or copy number alterations in NFE2L2/NRF2 or its degradation machinery (KEAP1, CUL3, or RBX1) in > 30% of NSCLC cell lines and patient tissues." (PMID 35184380, 2022). "Finally, recent treatment studies show good response for GLUT inhibitors in lung cancer PDX models TC333, TC453, and TC494 carrying KEAP1 or NFE2L2 mutations." (PMID 34429404, 2021). "For example, lung cancers frequently harbour mutations in NFE2L2 (nuclear factor, erythroid 2-like 2, encodes for NRF2) or KEAP1 (encodes for KEAP1, a negative regulator of NRF2), which results in the activation of antioxidant pathways, including SLC7A11 and NQO1 upregulation." (PMID 34205617, 2021). "Likewise, KEAP1-mutant lung cancer cells were shown to have higher levels of NRF2 and its downstream target SLC7A11." (PMID 34926310, 2021). "First of all, Genistein, used in combination with radiation, is able to increase the levels of ROS and to selectively augment the apoptotic rate in lung cancer cells through the reduction of KEAP1 promoter methylation that results in KEAP1 increased expression." (PMID 34141616, 2021). "The incidence of KEAP1 mutation is not high, especially in the Chinese lung cancer patients, with the reported incidence of about 20%." (PMID 35096557, 2021).
lung carcinoma (continued). "Additionally, by modulating the KEAP1/NRF2 pathway we were able to alter the sensitivity of lung cancer cells to artesunate." (PMID 33920029, 2021). "In this study, we further investigated how Nrf2 regulates motility in NSCLC cells based on our previous findings, which showed that high activation of Nrf2 due to Keap1 mutation promotes migration ability both in vitro and in vivo in EGFR-TKI resistant lung cancer cells." (PMID 33441941, 2021). "Downregulated KEAP1 has been frequently identified in lung cancer." (PMID 34136401, 2021). "Furthermore, we observed that breast cancer metastases at any site that harbor mutations in KEAP1, KRAS, and STK11, a triplet commonly associated with lung cancer, genomically resemble lung tumors (100% vs. 18%, p = 2e-8, n = 13)." (PMID 32374727, 2020). "Compared with A549/H460 lung cancer cell lines stably transfected with retroviral empty vector, the colony formation and migration of A549/H460 lung cancer cell lines stably transfected with WT KEAP1 were significantly decreased." (PMID 32576270, 2020). "However, mRNA levels of NRF2 and its target genes HO-1, GCLC, and FTH1 were significantly increased in the A549 or H460 lung cancer cell lines stably transfected with these five KEAP1 mutants." (PMID 32576270, 2020). "We further explored the effect of ML385 on the development of lung cancer cell lines with or without KEAP1 mutations." (PMID 32576270, 2020). "In contrast to the results of TCGA4,5, we detected low mutational frequencies of STK11, NF1, and BRAF were detected in LUAD and low mutational frequency of KEAP1 in both LUAD and LUSC, indicating the special molecular characteristics of Chinese lung cancer patients." (PMID 33219256, 2020). "Mutated KEAP1/NRF2 genes activate downstream oxidation reaction components (AREs), detoxification, and cell metabolism-related gene transcription levels, thereby changing cell oxidative stress levels to promote the occurrence of lung cancer." (PMID 32629428, 2020). "Moreover, colony formation and migration were increased in A549 and H460 lung cancer cell lines transfected with KEAP1 mutants." (PMID 32576270, 2020). "However, after being stably transfected with KEAP1 mutants, the colony formation and migration of A549/H460 lung cancer cell lines significantly increased." (PMID 32576270, 2020). "In this research, we explored the role of KEAP1 somatic mutations in the development of LSCC and whether a nuclear factor erythroid 2-related factor 2(NRF2) inhibitor be potential to target lung cancer carrying KEAP1/NRF2 mutations." (PMID 32576270, 2020). "Studies on chemoresistance suggested that selective inhibition of KEAP1 methylation in adenocarcinoma cells could represent a marker of radiosensitizing effects in lung cancer." (PMID 32971994, 2020). "We speculate that EGFR activation, in addition to NRF2 activating mutation or Keap1 dysfunction, might represent a complimentary mechanism for upregulating the serine biosynthetic pathway via NRF2-ATF4 axis in lung cancer." (PMID 31221965, 2019). "Most interestingly, our analysis of the pattern and density of KEAP1 promoter methylation in lung cancer cell lines showed that the first seven single CpG sites (1–7, P1a region) appeared to be significantly more methylated than the last six CpG group (8–13, P1b region) of the P1 promoter region." (PMID 31159323, 2019). "Notably, the protein level of KEAP1 was higher in patients with early stage (I) lung cancer than in patients with late-stage (III and IV) tumours." (PMID 31659154, 2019). "In this regard, loss-of-function (LOF) mutations in the KEAP1 gene, targeting the Kelch/DGR domain, normally required for NRF2 interaction and degradation, were initially identified in tissues or cell lines derived from lung cancer patients." (PMID 31097977, 2019). "Our data demonstrate that paclitaxel resistance is related to low KEAP1 expression in lung cancer." (PMID 31659154, 2019).